DDX4 (DEAD-box helicase 4)
Description:
ATP-dependent RNA helicase required during spermatogenesis. Required to repress transposable elements and preventing their mobilization, which is essential for the germline integrity (By similarity). Acts via the piRNA metabolic process, which mediates the repression of transposable elements during meiosis by forming complexes composed of piRNAs and Piwi proteins and governs the methylation and subsequent repression of transposons (By similarity). Involved in the secondary piRNAs metabolic process, the production of piRNAs in fetal male germ cells through a ping-pong amplification cycle (By similarity). Required for PIWIL2 slicing-triggered piRNA biogenesis: helicase activity enables utilization of one of the slice cleavage fragments generated by PIWIL2 and processing these pre-piRNAs into piRNAs (By similarity).
Synonyms: VASA
Tractability: Antibody: the Human Protein Atlas places it where antibodies can reach.
Gene: Protein-coding gene on chromosome 5 (55,738,017 to 55,817,157, forward strand). Ensembl gene ENSG00000152670.
Subcellular location: Cytoplasm; Cytoplasm, perinuclear region
Subcellular location (Human Protein Atlas): Cytosol; Nucleoplasm; Plasma membrane
Pathways (Reactome):
Gene expression (Transcription): PIWI-interacting RNA (piRNA) biogenesis
Signal Transduction: RND3 GTPase cycle
Gene Ontology:
Molecular function: molecular condensate scaffold activity; ATP hydrolysis activity; ATP binding; nucleic acid binding; RNA helicase activity
Biological process: flagellated sperm motility; cell differentiation; gamete generation; germ cell development; male meiosis I; male meiotic nuclear division; piRNA processing; spermatogenesis; transposable element silencing by piRNA-mediated DNA methylation; transposable element silencing by piRNA-mediated heterochromatin formation
Cellular component: cytoplasm; nucleus; P granule; pi-body; piP-body; perinuclear region of cytoplasm
Genetic constraint (gnomAD): Loss-of-function variants: 11 observed, 53.59 expected, observed/expected ratio (o/e) 0.21, 90% interval 0.13 to 0.34. The upper end of that interval is the gene's LOEUF score, 0.34, which puts it in group 1 of 6, group 1 being the genes least tolerant of losing a copy. Missense variants: 360 observed, 551.16 expected, observed/expected ratio (o/e) 0.65, 90% interval 0.6 to 0.71. Synonymous variants: 163 observed, 176.78 expected, observed/expected ratio (o/e) 0.92, 90% interval 0.81 to 1.05.
Homologues: Orthologues: chimpanzee DDX4 (100% identical), macaque DDX4 (99% identical), pig DDX4 (92% identical), rabbit DDX4 (90% identical), mouse Ddx4 (89% identical), rat Ddx4 (88% identical), guinea pig DDX4 (71% identical), zebrafish ddx4 (56% identical), tropical clawed frog ddx4 (54% identical), Drosophila melanogaster vas (42% identical), Caenorhabditis elegans glh-2 (36% identical), Caenorhabditis elegans glh-1 (36% identical), and 1 more. Paralogues in human: DDX3X (39% identical), DDX3Y (39% identical), DDX42 (26% identical), DDX17 (26% identical), DDX5 (26% identical), DDX43 (25% identical), DDX41 (24% identical), DDX46 (24% identical), DDX53 (23% identical), DDX23 (23% identical), DDX59 (22% identical), DDX52 (21% identical), and 26 more.
Diseases named in the same sentence as DDX4 in open-access papers:
DDX4 is named in the same sentence as 46 diseases in open-access papers, as found by Europe PMC text mining. Sharing a sentence is not in itself a finding about the gene and the disease. The quoted sentences say what the papers report.
infertile (13 papers, 2011 to 2025). "Changes observed in the genes Dazl and Ddx4, germ cell markers, and Amh, a marker for Sertoli cells, in testicular tissues have been associated with fertility disorders and infertility." (PMID 40186081, 2025). "In DDX4, the homozygous missense variant c.1532 C>T p.(Ala511Val) was identified in an infertile man (M928) with cryptozoospermia due to predominant round spermatid arrest in the testicular tissue." (PMID 39122675, 2024). "Whether the infertility phenotype observed in our Ddx4-Cre;Dcr1fx/fx is consecutive either to the loss of endo-siRNAs and/or miRNAs is still uncertain." (PMID 21998645, 2011). "In addition, the chicken DEAD-Box Helicase 4 (DDX4) gene, essential for formation of germ cell lineage formation, was disrupted by transcription activator-like effector nucleases (TALENs), resulting in the loss of PGCs and infertile hens." (PMID 37107658, 2023). "We observed infertility of Ggpps−/− Ddx4-Cre mice that displayed a Sertoli-cell-only syndrome phenotype, which resulted from abnormal spermatogonial differentiation and SSC depletion during the prepubertal stage." (PMID 27374985, 2016). "All adult Ddx4-KO males were infertile and exhibited a drastic reduction in testis size compared to age-matched WT controls." (PMID 27149259, 2016). "We have previously shown that the spermatogonia-specific deletion of Dicer1, using Cre under the control of the Ddx4 promoter, leads to infertility." (PMID 25244517, 2014). "To further characterize the events that lead to infertility in Ddx4-Cre;Dcr1fx/fx mutant mice, we compared the development of control and mutant testes during the early phases of the first spermatogenic wave, from P5 to P21." (PMID 21998645, 2011). "Interestingly, the ablation of either Dicer1 or Dgcr8 in the germ cell lineage using the Ddx4:Cre transgene led to complete infertility." (PMID 25244517, 2014). "The rest of Ggppsfl/fl, Ddx4-Cre females showed a delayed first litter (day 78.7 ± 3.9 vs. 104.7 ± 8.7), reduced litter numbers (8.3 ± 0.4 vs. 2.3 ± 0.7) and the reduced litter size (6.6 ± 0.4 vs. 3.8 ± 0.6), and they eventually became infertile after 28 weeks." (PMID 28072828, 2017).
male infertility (9 papers, 2018 to 2024). The inability of the male to effect fertilization of an ovum after a specified period of unprotected intercourse. "Male infertility ensues after Ddx4 KO, while the Ddx4 mutation has minimal influence on female fertility, although oocytes with elevated levels of Ddx4 have been observed." (PMID 38785936, 2024). "Genes SYCP3 and DDX4, which contained both hypo-DMRs and hypo-DMCs identified in our study, play a major role in spermatogenesis insofar as either mutation or aberrant methylation of these genes associate to male infertility." (PMID 29843609, 2018). "The conditional ablation of NRF1 in gonocytes dramatically down-regulates several germline genes (Dazl, Lin28a, Ddx4), blocks germ cell proliferation, and subsequently leads to male infertility in mice suggesting an important role of NRF1 in regulation of some GRRs." (PMID 38715099, 2024). "Transcriptomic changes triggered by RNA helicases initiate differentiation processes and result in a development of cell lineages Below, we describe examples of DEAD-box helicases: DDX3Y, DDX25, and DDX4/VASA in contexts of germline generation, spermatogenesis, and male infertility." (PMID 32328902, 2020). "DDX4 KO also resulted in male infertility and their proliferative activity of primordial germ cells was reduced; DDX4-null spermatogonia failed to reach the fertilized egg stage and undergo apoptosis." (PMID 38912589, 2024).
Azoospermia (8 papers, 2015 to 2023). Absence of any measurable level of sperm,whereby spermatozoa cannot be observed even after centrifugation of the semen pellet. "Additionally, germ cell-specific (DEAD-box helicase 4), seminal vesicle-specific (Semenogelin 1), and prostate-specific (Transglutaminase 4) mRNAs in seminal plasma could be markers for identifying the presence of germ cells or the rough localization of complete obstructive azoospermia." (PMID 35211476, 2021). "DDX4, recognized as a general germ cell marker present across all stages of germ cell development, including spermatogonia, spermatocytes, and round spermatids, has been chosen as one of the protein biomarkers in seminal plasma for diagnosing non-obstructive azoospermia (NOA)." (PMID 37799407, 2023).
neuroblastoma (6 papers, 2016 to 2024). Neuroblastoma (NB) is the most common solid, extracranial childhood tumor. "Interestingly, genome-wide association studies (GWAS) have identified single-nucleotide polymorphisms (SNPs) in DDX4 as highly associated with neuroblastoma tumors." (PMID 26834021, 2016). "Later on, the same group reported that common variants in BARD1 gene were associated with high-risk neuroblastoma, and polymorphisms within DUSP12, DDX4, IL31RA, and HSD17B12 were associated with low-risk neuroblastoma." (PMID 31341530, 2019). "Through a genomewide association study (GWAS) of sporadic neuroblastoma, we have reported common single nucleotide polymorphisms (SNPs) associated with neuroblastoma susceptibility at CASC154, BARD15, LMO16, DUSP127, HSD17B127, DDX4/IL31RA7, HACE18 and LIN28B8 loci." (PMID 28667701, 2017).
ovarian carcinoma (4 papers, 2016 to 2019). A malignant neoplasm originating from the surface ovarian epithelium. "Several investigators have demonstrated the occurrence of Ddx4+ cells in epithelial ovarian cancer (EOC) samples as well as in ovarian tumor cell lines." (PMID 31261822, 2019). "It has been reported that DDX4 colocalizes with the cancer stem cell marker CD133 in ovarian cancers." (PMID 27835882, 2016). "In addition, by inducing the overexpression of Ddx4 in SKOV-3 ovarian cancer cells, they demonstrated that a number of proteins were up- or down-regulated, and, in particular, that the 14-3-3σ proteinwas down-regulated at the post-transcriptional level." (PMID 31261822, 2019). "Moreover, it has been reported that DDX4 is expressed in several ovarian cancer cells and tissues, and its overexpression stimulates cell cycle progression by abolishing the G2 checkpoint." (PMID 30380781, 2018). "The authors thus suggested that Ddx4 is potentially involved in EOC progression, and that it is a tumorigenesis marker in ovarian cancer." (PMID 31261822, 2019). "Based on these findings, the fate of small Ddx4+ cells detected in OSE is still debated, but it is a common opinion that these cells, under different stimuli, are not only capable of promoting neo-oogenesis but also participate in epithelium repair after ovulation and ovarian cancer development." (PMID 31261822, 2019). "On the other hand, particularly in the postmenopausal age in which the incidence of the ovarian cancer is significantly higher, the chronic hormone stimulation provided by gonadotropins, such as FSH, may drive the acquisitionof molecular derangements of Ddx4+ cells that contribute to carcinogenesis." (PMID 31261822, 2019).
ovarian tumor (3 papers, 2015 to 2019). "In agreement with the data from Ddx4-Cre;Rb1fl/∆ mice, ~30% of Blimp1-Cre;Rb1fl/∆ females developed ovarian tumors." (PMID 26176933, 2015). "The pathophysiological role of this cell population in aged women is still debated since OSCs, under appropriate stimuli, differentiate into somatic cells, and the occurrence of Ddx4+ cells in ovarian tumor samples also suggests their potential involvement in carcinogenesis." (PMID 31261822, 2019). "The localization of FOXL2, INHA, FOXO1, AMH, and DDX4 was detected in the granulosa cell or oocyte compartment of control ovaries, while ovarian tumor tissues from TGFBR1-CAG9Cre mice were immunoreactive with FOXL2, INHA, and FOXO1, supporting the development of GCTs in these mice." (PMID 29221447, 2017).
teratoma (3 papers, 2015 to 2019). A non-seminomatous germ cell tumor characterized by the presence of various tissues which correspond to the different germinal layers (endoderm, mesoderm, and ectoderm). "Further, Rb1 was successfully deleted in teratoma tissues, and we found both Ddx4-cre transgene positive and negative teratomas, suggesting that teratomas arise from oocytes that have completed the first meiotic division." (PMID 26176933, 2015).
ZIKV infection (3 papers, 2018 to 2023). "Quantification further showed that DDX4+ spermatogenic cells significantly decreased after ZIKV infection whereas DDX4+ MAC+ spermatogenic cells, C1q+ cells, and S100A4+ cells were all increased, displaying features similar to those in A6 mice." (PMID 37120617, 2023). "The infection rate of each type of these cells was then determined by measuring the co-localization signals, and it was clear that S100A4+ macrophages replaced DDX4+ cells as the main target cells at late stage of ZIKV infection." (PMID 33315931, 2020). "We found that human GCs are permissive for ZIKV infection as indicated by colocalization of ZIKV-E and DDX4." (PMID 29844387, 2018). "However, the ZIKV antigen was largely located in S100A4+ macrophages instead of DDX4+ spermatogenic cells at this time, indicating that intraluminal S100A4+ macrophages replaced spermatogenic cells to support ZIKV infection." (PMID 33315931, 2020).
gastric cancer (2 papers, 2018 to 2025). A primary or metastatic malignant neoplasm involving the stomach. "Of these, LRASM1 and DDX4 two proteins were altered in both the gastric cancer cell lines treated with PEC." (PMID 30380781, 2018).
premature ovarian failure (2 papers, 2020 to 2021). "Since the FSHR3 variant is apparently involved in a few biological processes, as premature ovarian failure and aging, as well as OC development, it is conceivable that, even in mesodermal differentiation, the FSHR3 isoform is expressed by Ddx4+ cells though this was not assessed in our study." (PMID 32847044, 2020).
seminoma (2 papers, 2015 to 2016). A radiosensitive malignant germ cell tumor found in the testis (especially undescended), and extragonadal sites (anterior mediastinum and pineal gland). "On the other hand, premalignant testis adjacent to seminoma display downregulation of DDX4 expression." (PMID 26843623, 2016). "Surprisingly, expression of germ cell marker DDX4 suggests that spermatogenesis is retained in premalignant testis tissues adjacent to nonseminoma, but not those adjacent to seminoma." (PMID 26843623, 2016). "Namely, we found that PIWIL1/2/4 and DDX4 are concertedly expressed in preneoplastic testis tissue adjacent to nonseminoma but are downregulated in those adjacent to seminoma." (PMID 26843623, 2016).
colorectal cancer (1 paper, 2014). A primary or metastatic malignant neoplasm that affects the colon or rectum. "To do this, we selected a small sub-group of these genes that remained transcriptionally silenced in the colorectal cancer cell lines HCT116 and SW480 (ARRDC5, C4orf17, C20orf201, DDX4, NT5C1B, STRA8, TDRD12)." (PMID 25594001, 2014).
endometriosis (1 paper, 2015). The growth of functional endometrial tissue in anatomic sites outside the uterine body. "Nevertheless, the presence of ovarian germ line stem cells as contributors to endometriosis progression remains to be further studied through functional analysis in isolated DDX4/IFITM3-positive cells." (PMID 26446766, 2015). "The identification of germ cell-specific proteins DDX4 and IFITM3 provides the first evidence of ovarian-sourced cells in ovarian endometriotic lesions and opens up new directions towards understanding the still confusing pathogenesis of endometriosis." (PMID 26446766, 2015). "In this context, up regulation of DDX4 and IFITM3 proteins in ovarian-sourced stem cells, as well as OCT4 in eMSC, could correlate with the molecular pathway towards the malignant forms of the endometriosis lesion." (PMID 26446766, 2015).
female infertility (1 paper, 2017). Diminished or absent ability of a female to achieve conception. "Among 7 female Ggppsfl/fl, Ddx4-Cre mice, 4 mice revealed complete female infertility." (PMID 28072828, 2017).
glioma (1 paper, 2022). A benign or malignant brain and spinal cord tumor that arises from glial cells (astrocytes, oligodendrocytes, ependymal cells). "Consistent with this, high expression of the genes associated with PGC fate determination usually did not lead to poor outcomes of gliomas, such as KIT, DND1, NANOS3 and DDX4." (PMID 36435765, 2022).
iron deficiency (1 paper, 2023). "To evaluate the effect of iron deficiency on cell proliferation of germ cells, primary spermatocyte and Sertoli cells in testis and epididymis, we tested the co-staining of DDX4+/Ki67+, SCP3+/Ki67+ GATA1+/Ki67+ and GATA1+/BrdU+." (PMID 37346174, 2023). "Iron deficiency not only decreases electron transport, oxidative phosphorylation level, and ATP production but also suppresses the activity of ribonucleotide reductase and the expression of Ki67, DDX4, GATA1, and SCP3, indicating that Sev affects the spermatogenesis and development." (PMID 37346174, 2023).
leukemia (1 paper, 2007). A malignant (clonal) hematologic disorder, involving hematopoietic stem cells and characterized by the presence of primitive or atypical myeloid or lymphoid cells in the bone marrow and the blood. "Two of the selected genes could not be detected in the majority of the samples in either normal or leukemia bone marrow (HOXA10 and DDX4) and were therefore excluded from further analysis." (PMID 17712416, 2007).
Obesity (1 paper, 2025). Accumulation of substantial excess body fat. "We also showed that Vasa/DDX4 expressing cells in the adipose tissue were increased upon HFD or obesity conditions not only in fruit flies but also in mammals." (PMID 40136664, 2025).
ovarian endometriosis (1 paper, 2015). A non-neoplastic disorder characterized by the growth of endometrial tissue in the ovaries. "Ten paraffin-embedded ovarian endometriosis samples were screened for germ cell-specific proteins DDX4 (VASA) and IFITM3, and its relation with stem cell marker OCT4, proliferation marker PCNA and estrogen receptor alpha (ESR1), by immunohistochemistry, immunofluorescence and PCR." (PMID 26446766, 2015). "We identified DDX4 and IFITM3 proteins in isolated and clusters of cells in ovarian endometriosis lesions." (PMID 26446766, 2015).
Parkinson disease (1 paper, 2015). A progressive degenerative disorder of the central nervous system characterized by loss of dopamine producing neurons in the substantia nigra and the presence of Lewy bodies in the substantia nigra and locus coeruleus. "It is interesting to compare phase separation of Ddx4 proteins into organelles with the aggregation of proteins more generally into the amyloid fibrils that are associated with misfolding conditions, including Alzheimer’s and Parkinson’s diseases." (PMID 25747659, 2015).
renal cell carcinoma (1 paper, 2020). "Downregulation of piRNA pathway genes in cancer may be uncommon but have been reported in testicular germ cell tumor (PIWIL1, PIWIL2, PIWIL4 and DDX4) and renal cell carcinoma (PIWIL1, PIWIL2 and PIWIL4) and now, also in our expression study for PIWIL2, PIWIL4 and TDRD1." (PMID 33374923, 2020).
serous ovarian cancer (1 paper, 2020). "Ddx4 expression has been correlated with poor prognosis of serous ovarian cancer (OC), while the potential role of Ddx4+ cells in non-serous epithelial OC (NS-EOC) is almost unexplored." (PMID 32847044, 2020).
small cell lung carcinoma (1 paper, 2023). Small cell lung cancer (SCLC) is a highly aggressive malignant neoplasm, accounting for 10-15% of lung cancer cases, characterized byrapid growth, and early metastasis. "DDX4, a conserved germline factor and RNA helicase, increases small cell lung cancer cell survival by regulating DNA damage and immune response pathways and contributes to cisplatin-mediated drug resistance." (PMID 36653474, 2023). "Here we demonstrate that DEAD-box helicase 4 (DDX4), a germline factor and RNA helicase conserved in all multicellular organisms, contributes to increased cell motility and cisplatin-mediated drug resistance in small cell lung cancer (SCLC) cells." (PMID 36653474, 2023).
Testicular atrophy (1 paper, 2024). Wasting (atrophy) of the testicle (the male gonad) manifested by a decrease in size and potentially by a loss of fertility. "After treatment of 8-week-old male mice with tamoxifen, acquired deletion of Chd8 in germ cells (Ddx4-CreERT2; Chd8F/F) resulted in gradual testicular atrophy and a defect in sperm production." (PMID 38224953, 2024).